FGF16 (fibroblast growth factor 16)
Description:
Plays an important role in the regulation of embryonic development, cell proliferation and cell differentiation, and is required for normal cardiomyocyte proliferation and heart development.
Synonyms: FGF-16; MF4
Tractability: Small molecule: it belongs to a druggable protein family. Antibody: its Gene Ontology location is reachable by antibodies, with high confidence; UniProt places it where antibodies can reach, with medium confidence.
Gene: Protein-coding gene on chromosome X (77,447,389 to 77,457,278, forward strand). Ensembl gene ENSG00000196468.
Subcellular location: Secreted
Pathways (Reactome):
Signal Transduction: FGFR2c ligand binding and activation; FGFR3c ligand binding and activation; FGFR4 ligand binding and activation; FRS-mediated FGFR2 signaling; FRS-mediated FGFR3 signaling; FRS-mediated FGFR4 signaling; Negative regulation of FGFR2 signaling; Negative regulation of FGFR3 signaling; Negative regulation of FGFR4 signaling; PI-3K cascade:FGFR2; PI-3K cascade:FGFR3; PI-3K cascade:FGFR4; PI3K Cascade; PI5P, PP2A and IER3 Regulate PI3K/AKT Signaling; PIP3 activates AKT signaling; Phospholipase C-mediated cascade; FGFR2; Phospholipase C-mediated cascade; FGFR3; Phospholipase C-mediated cascade; FGFR4; RAF/MAP kinase cascade; SHC-mediated cascade:FGFR2; SHC-mediated cascade:FGFR3; SHC-mediated cascade:FGFR4
Disease: Activated point mutants of FGFR2; Constitutive Signaling by Aberrant PI3K in Cancer; Signaling by FGFR2 in disease; Signaling by FGFR3 in disease; Signaling by activated point mutants of FGFR3
Gene Ontology:
Molecular function: protein binding; fibroblast growth factor receptor binding; growth factor activity
Biological process: positive regulation of endothelial cell chemotaxis to fibroblast growth factor; regulation of endothelial cell proliferation; regulation of MAP kinase activity; regulation of sprouting angiogenesis; animal organ morphogenesis; cell-cell signaling; fibroblast growth factor receptor signaling pathway; neurogenesis; positive regulation of cell population proliferation; positive regulation of MAPK cascade; regulation of cell migration; response to temperature stimulus; signal transduction
Cellular component: cytoplasm; extracellular region
Homologues: Orthologues: chimpanzee FGF16 (100% identical), macaque FGF16 (100% identical), mouse Fgf16 (99% identical), rabbit FGF16 (99% identical), guinea pig FGF16 (98% identical), pig FGF16 (98% identical), rat Fgf16 (98% identical), dog FGF16 (98% identical), tropical clawed frog fgf16 (86% identical), zebrafish fgf16 (79% identical). Paralogues in human: FGF9 (71% identical), FGF20 (65% identical), FGF3 (34% identical), FGF5 (33% identical), FGF10 (30% identical), FGF7 (30% identical), FGF1 (29% identical), FGF13 (29% identical), FGF2 (29% identical), FGF4 (29% identical), FGF22 (29% identical), FGF6 (29% identical), and 9 more.
Diseases named in the same sentence as FGF16 in open-access papers:
FGF16 is named in the same sentence as 32 diseases in open-access papers, as found by Europe PMC text mining. Sharing a sentence is not in itself a finding about the gene and the disease. The quoted sentences say what the papers report.
cardiac hypertrophy (12 papers, 2013 to 2025). "CFs-associated FGF2 and FGF16 contribute to cardiac hypertrophy via stimulating CMs in a paracrine fashion." (PMID 40843168, 2025). "GATA4 regulates neonatal heart regeneration through regulating expression of FGF16, and overexpression of FGF16 via adeno-associated virus in Gata4-ablated mice heart could partially rescue cardiac hypertrophy and improve cardiac function after injury." (PMID 39544432, 2024). "In addition, a recent study has shown that cardiac-specific overexpression of Fgf16 via AAV9 in Gata4-deficient hearts rescued cryoinjury-induced cardiac hypertrophy, promoted cardiomyocyte replication and improved heart function after injury." (PMID 36399125, 2022). "A recent study on a mouse model, has shown that FGF16 prevents angiotensin II-induced cardiac hypertrophy and fibrosis by antagonizing FGF2." (PMID 40843168, 2025). "FGF16 also plays a role in cardiac hypertrophy, though the role is the opposite of FGF2 in cardiac hypertrophic remodeling." (PMID 39452290, 2024). "The hierarchical cluster heatmap and Venn diagram indicated that 5 of 22 FGF genes (FGF1, FGF5, FGF12, FGF16, and FGF18) were associated with myocardial hypertrophy." (PMID 36871047, 2023). "Fgf16 has been described to prevent cardiac hypertrophy and fibrosis by competing with Fgf2 for the binding site of the FGF receptor 1c, Fgfr1c, in a paracrine manner." (PMID 25333065, 2014). "The hearts of the Fgf16−/− mice were more hypertrophic and fibrotic than in wild-type mice suggesting that Fgf16 prevents angiotensin II-induced cardiac hypertrophy and fibrosis." (PMID 25333065, 2014). "Increased expression levels of marker genes for cardiac hypertrophy and/or fibrosis also support promoted angiotensin II-induced cardiac hypertrophy and fibrosis in Fgf16 knockout mice." (PMID 23600527, 2013). "Here, we report a possible mechanism whereby Fgf16 prevents angiotensin II-induced cardiac hypertrophy and fibrosis." (PMID 23600527, 2013). "Angiotensin II-induced cardiac hypertrophy and fibrosis were shown to be significantly promoted by enhancing Tgf- β1 expression in Fgf16 knockout mice." (PMID 24046748, 2013). "The phenotype of Fgf16 knockout mice indicates that Fgf16 probably prevents angiotensin II-induced cardiac hypertrophy and fibrosis by repressing Tgf-β1 expression in mice." (PMID 23600527, 2013). "Angiotensin II-induced cardiac hypertrophy and fibrosis were significantly promoted by enhancing Tgf-β1 expression in Fgf16 knockout mice." (PMID 23600527, 2013). "To elucidate the pathophysiological role of Fgf16 in the heart, we examined angiotensin II-induced cardiac hypertrophy and fibrosis in Fgf16 knockout mice." (PMID 23600527, 2013). "Histological analysis indicates that angiotensin II-induced cardiac hypertrophy and fibrosis are significantly promoted in Fgf16 knockout mice." (PMID 23600527, 2013). "In addition, cardiac-specific overexpression of FGF16 promoted cardiomyocyte replication but inhibited cryoinjury-induced cardiac hypertrophy, which ultimately improved heart function after injury." (PMID 35351862, 2022). "FGF16 may prevent cardiac hypertrophy and fibrosis by competing with FGF2 for the binding site of FGFR1c in a paracrine manner." (PMID 24046748, 2013). "Angiotensin II-induced cardiac hypertrophy and fibrosis are significantly promoted by increasing the expression of TGF-β1 in FGF16 knockout mice." (PMID 27803896, 2016). "While FGF16 and FGF21 may prevent cardiac hypertrophy and fibrosis, FGF2 and FGF23 display the opposite effect." (PMID 27184924, 2016).
myocardial infarction (5 papers, 2014 to 2025). Gross necrosis of the myocardium, as a result of interruption of the blood supply to the area, as in coronary thrombosis. "Cardiac disorders including myocardial infarction and atrial fibrillation follow the FGF16 mutated trait, indicating a relationship between the FGF16 mutation and cardiac disease." (PMID 27803896, 2016). "The smoking mother of the proband (III-10), who was heterozygous for the FGF16 mutation, had a myocardial infarction at the age of 46 years." (PMID 25333065, 2014). "Cardiac disorders, including myocardial infarction and atrial fibrillation followed the X-linked FGF16 mutated trait in one large family." (PMID 25333065, 2014). "Interestingly, three individuals in family 1, carrying the nonsense mutation in FGF16, had myocardial infarction at an early age." (PMID 25333065, 2014). "Intramyocardial injection of FGF16 recombinant protein in db/db mice after myocardial infarction improved cardiac function and reduced interstitial fibrosis and monocyte infiltration after two and four weeks." (PMID 31801200, 2019). "FGF16 was shown to provide cardiac protection in diabetes after myocardial infarction." (PMID 36650549, 2023). "FGF16, the only FGF family member that shows preferential expression in the postnatal heart, has been shown a direct cardioprotective effect against myocardial infarction through intramyocardial injection of FGF16 protein in db/db type 2 diabetic mice." (PMID 40585885, 2025).
atrial fibrillation (2 papers, 2014 to 2016). A disorder characterized by an electrocardiographic finding of a supraventricular arrhythmia characterized by the replacement of consistent P waves by rapid oscillations or fibrillatory waves that vary in size, shape and timing and are accompanied by an irregular ventricular response. "One male cousin (IV-12) found later to have the FGF16 mutation had a manifest atrial fibrillation requiring defibrillation at the age of 25 years." (PMID 25333065, 2014).
cleft palate (2 papers, 2019 to 2022). Cleft palate is a fissure type embryopathy that affects the soft and hard palate to varying degrees. "Mutations in Fgf16 or Fgfr2 are associated with cleft palate, and suppression of Fgfr signaling via Fgfr kinase inhibitors causes palate defects." (PMID 31596367, 2019). "Subsequently, we correlated our data to gene expression using qPCR, focusing on Fgf16 and Tbx22, previously reported to be associated with cleft palate formation." (PMID 31596367, 2019).
lung carcinoma (2 papers, 2021 to 2023). "In clinical lung cancer tissues, FGF16 is overexpressed and its high level is negatively associated with the low level of miR-520b." (PMID 33758783, 2021). "Our data revealed that high expression of FGF16 is closely associated with low level of miR-520b in these 30 cases of human lung cancer samples (R = −0.6939, P < 0.01)." (PMID 33758783, 2021). "Apart from developmental role in cardiomyocytes, FGF16 has been identified to be potentially involved in hepatocellular carcinoma as well as in lung cancer." (PMID 37222403, 2023). "Next, we tried to investigate the modulation of miR-520b on FGF16 in lung cancer A549 and H1299 cell lines through RT-PCR and immunoblotting assays." (PMID 33758783, 2021). "We first evaluated the level of FGF16 in lung cancer A549 cells after the cells were treated with miR-520b, anti-miR-520b, or anti-miR-520b/si-FGF16 via immunoblotting analysis." (PMID 33758783, 2021). "For the function investigation, we are interested in the role of FGF16 in miR-520b-regulated growth of lung cancer." (PMID 33758783, 2021). "As a tumor suppressor, miR-520b can suppress the growth of lung cancer and its target gene FGF16 is able to reverse the inhibitory effect of miR-520b on lung cancer growth." (PMID 33758783, 2021). "To clarify the relationship of FGF16 and miR-520b in lung cancer, we further analyzed the level of miR-520b using above 30 cases of human lung cancer tissues." (PMID 33758783, 2021). "In this study, we present the novel function of FGF16 and the regulation of miR-520b on FGF16 in lung cancer progression." (PMID 33758783, 2021). "Taken together, our results suggest that miR-520b-regulated FGF16 is involved in the growth of lung cancer." (PMID 33758783, 2021). "In this study, we present the novel function of FGF16 in lung cancer and its regulation factor at the post-transcription level." (PMID 33758783, 2021). "To further confirm the results obtained from lung cancer A549 cell line, we treated another lung cancer cell line H1299 with miR-520b and analyzed the change in RNA and protein levels of FGF16." (PMID 33758783, 2021). "Then, we investigated the mechanism by which miR-520b decreased the mRNA level of FGF16 in lung cancer cells." (PMID 33758783, 2021). "Our study provides a promising evidence for FGF16 as the potential target in anti-lung cancer drug study." (PMID 33758783, 2021). "Our finding can identify FGF16 as a novel biomarker for lung cancer and also provide the potential utility of miR-520-targeting FGF16 in lung cancer therapy." (PMID 33758783, 2021). "We find that FGF16 is a novel target gene of tumor suppressor miR-520b in lung cancer." (PMID 33758783, 2021). "In conclusion, FGF16 is negatively correlated with miR-520b in human clinical lung cancer samples." (PMID 33758783, 2021). "Notably, FGF16 is highly expressed in lung cancer and it is able to reverse miR-520b-inhibited lung cancer." (PMID 33758783, 2021). "In this study, first we are interested in the expression of FGF16 in clinical lung cancer samples." (PMID 33758783, 2021). "Moreover, FGF16 silence using RNA interference is capable of doing great damage to anti-miR-520b-accelerated growth of lung cancer." (PMID 33758783, 2021). "It indicates that high FGF16 in lung cancer can serve as a biomarker and its regulating miRNA miR-520b may be used in clinical treatment for lung cancer." (PMID 33758783, 2021). "Yet, the function of FGF16 in the development of lung cancer remains largely unexplored." (PMID 33758783, 2021). "Our data showed that FGF16 is markedly overexpressed in clinical lung cancer samples." (PMID 33758783, 2021). "In further investigation, we want to know how FGF16 is regulated by miR-520b in lung cancer." (PMID 33758783, 2021). "Next, we are wondering whether miR-520b is able to affect the expression of FGF16 in lung cancer cells." (PMID 33758783, 2021).
lung carcinoma (continued). "Furthermore, both the transcription and translation levels of FGF16 are restrained by miR-520b in lung cancer cells." (PMID 33758783, 2021). "Our data showed that miR-520b could directly bind to 3′UTR of FGF16 mRNA to make its cleavage, leading to the reduction of FGF16 mRNA in lung cancer cells." (PMID 33758783, 2021). "We observed FGF16 overexpression in all 30 cases of human lung cancer tissues." (PMID 33758783, 2021). "For lung cancer, FGF16 may serve as a novel biomarker and miR-520b/FGF16 may be useful in clinical treatment." (PMID 33758783, 2021). "Thus, our finding indicates that FGF16 is a new target gene of miR-520b in lung cancer." (PMID 33758783, 2021). "However, the function of FGF16 and its regulation in lung cancer progression are still unclear." (PMID 33758783, 2021). "Therefore, our data imply that FGF16 is a direct target gene of miR-520b in lung cancer." (PMID 33758783, 2021). "Interestingly, we observed a negative correlation of FGF16 with miR-520b in human lung cancer tissues." (PMID 33758783, 2021). "First, we tested the level of FGF16 in 30 paired lung cancer tissues and noncancerous tissues." (PMID 33758783, 2021). "Yet, the function of FGF16 in the development of lung cancer is not determined." (PMID 33758783, 2021).
ovarian carcinoma (2 papers, 2015 to 2021). A malignant neoplasm originating from the surface ovarian epithelium. "FGF16 is implicated in the progression of some specific types of cancers, such as embryonic carcinoma, ovarian cancer, and liver cancer." (PMID 33758783, 2021). "As the sixteenth member of FGF family, FGF16 is involved in the progression of some specific types of cancers, such as embryonic carcinoma, ovarian cancer, and liver cancer." (PMID 33758783, 2021). "We showed earlier that PITX2 interacts with and regulates, FGF16, a prime inducer of invasion of ovarian cancer cells." (PMID 26298390, 2015). "FGF16 in combination with WNT pathway is able to drive the ovarian cancer progression." (PMID 33758783, 2021). "FGF16 together with WNT signaling enhance the development of ovarian cancer." (PMID 33758783, 2021).
breast carcinoma (1 paper, 2023). "In continuation to these findings, we attempted to investigate the potential oncogenicity of FGF16 and the underlying mechanism in breast cancer progression." (PMID 37222403, 2023). "Here, we report the elevated expression of FGF16 in human breast tumor and investigate its potential involvement in breast cancer progression." (PMID 37222403, 2023). "In conclusion, here we present a comprehensive mechanistic investigation on oncogenic potential of FGF16 in breast cancer through the initiation of EMT and invasion." (PMID 37222403, 2023). "Q-PCR assay (n = 5 paired and 8 orphan; P<0.005) and immuno-flourescence-based IHC analysis (n=6 Paired) demonstrated elevated expression of FGF16 in human breast cancer compared to normal breast tissues." (PMID 37222403, 2023). "In summary, elevated expression in tumor samples and induction of cell invasiveness/migration supported the oncogenic potential of FGF16 in breast cancer." (PMID 37222403, 2023). "In the present study, the oncogenic potential of FGF16 in breast cancer progression has been demonstrated, where the activation of EMT was found to be critical." (PMID 37222403, 2023). "To investigate the potential role of FGF16 in breast cancer development, we explored whether it can trigger EMT with immortalized human mammary epithelial cell-line MCF10A." (PMID 37222403, 2023). "The breast cancer cells were found to adopt the GLUT3–PFKFB4 axis under influence of FGF16." (PMID 37222403, 2023).
breast tumor (1 paper, 2023). "Our investigation was initiated with the finding of elevated expression of FGF16 in human breast tumor samples." (PMID 37222403, 2023).
cardiac failure (1 paper, 2013). "Compensatory cardiac failure response to angiotensin II is promoted in Fgf16 knockout mice." (PMID 23600527, 2013).
cardiomyopathy (1 paper, 2022). A disease of the heart muscle or myocardium proper. "Of relevance to the current study, FGF9 and FGF16, which belong to the same FGF9 subfamily as FGF20, play pivotal roles in protecting against cardiomyopathy." (PMID 35351862, 2022).
diabetic foot ulcers (1 paper, 2021). "FGF1, FGF2, FGF4, FGF7, FGF16, FGF21, and FGF23 have been found to have good therapeutic outcomes for diabetic foot ulcers." (PMID 34831463, 2021).
dilated cardiomyopathy (1 paper, 2013). Cardiomyopathy which is characterized by dilation and contractile dysfunction of the left and right ventricles. "In addition, dilated cardiomyopathy is also slightly induced in Fgf16 knockout mice with angiotensin II infusion." (PMID 23600527, 2013).
embryonic carcinoma (1 paper, 2021). "As one of the 22 members of FGF family in vertebrates, FGF16 can promote the survival of human embryonic carcinoma cells." (PMID 33758783, 2021). "Four FGFs such as FGF16, FGF10, FGF17, and FGF18 can increase the survival of human embryonic carcinoma cells." (PMID 33758783, 2021).
emphysema (1 paper, 2022). "Among the 15 protein fingerprint that correlated with the prevalence of emphysema and the incidence of exacerbations, FGF-16, a growth factor contributing to tissue regeneration, may represent a starting point for the development of new therapeutics." (PMID 36480517, 2022).
Epstein-Barr virus infection (1 paper, 2022). An infection that is caused by Epstein-Barr virus. "Finally, four significant KEGG enrichment pathways were identified (P < 0.05): beta-Alanine metabolism (SMOX, HIBCH), Pathways in cancer (GLI2, AR, TXNRD3, TRAF3, FGF16), Non-homologous end-joining (MRE11), Epstein-Barr virus infection (TRAF3, PSMD13, SIN3A)." (PMID 36330154, 2022). "Finally, the results of KEGG enrichment analysis showed four significantly enriched pathways (P < 0.05): beta-Alanine metabolism (SMOX, HIBCH), Pathways in cancer (GLI2, AR, TXNRD3, TRAF3, FGF16), Non-homologous end-joining (MRE11), Epstein-Barr virus infection (TRAF3, PSMD13, SIN3A)." (PMID 36330154, 2022).
liver cancer (1 paper, 2021). An epithelial or non-epithelial malignant neoplasm that arises from the liver. "FGF16 can be regulated by miR-520f in liver cancer development." (PMID 33758783, 2021).
prostate carcinoma (1 paper, 2012). A carcinoma that arises from epithelial cells of the prostate gland. "Noteworthy, the FGF16 gene that encodes a mitogenic growth factor was overexpressed in the PP adipose tissue of men with prostate cancer." (PMID 23009291, 2012).
rectal adenocarcinoma (1 paper, 2023). "Out of all 155 target genes, only higher BIRC2 and FGF16 transcript levels were significantly associated with increased and decreased overall survival, respectively, in rectal adenocarcinoma." (PMID 37345032, 2023).